DEAF1 (DEAF1 transcription factor)
Diseases named in the same sentence as DEAF1 in open-access papers (continued):
Sharing a sentence is not in itself a finding about the gene and the disease.
autism spectrum disorder (1 paper, 2023). A spectrum of developmental disorders that includes autism, and Asperger syndrome. "In summary, our study has revealed the involvement of four known genes (DEAF1, CLCN3, KMT2C, and DHX30) as well as two novel genes (TRPC4 and SCFD2) in autism spectrum disorder across six families from Qatar." (PMID 38025430, 2023).
autoimmune disorders (1 paper, 2023). "Deformed Epidermal Autoregulatory Factor 1 (DEAF1) is a transcription factor associated with autoimmune disorders and has been previously found to bind TTCG motifs." (PMID 38200810, 2023).
channelopathies (1 paper, 2018). "Furthermore, both the gain- and loss-of-function phenotype can be observed in other channelopathies such as KCNA2, GRIN1, and DEAF1 gene mutations." (PMID 29545233, 2018).
chondrosarcoma (1 paper, 2013). A malignant cartilaginous matrix-producing mesenchymal neoplasm arising from the bone and soft tissue. "In line with that observed in SW872 cells, the increases in GDF5 expression were not significant following Sp1, Sp3 and P15 depletion but a significant fold change was observed upon DEAF-1 knockdown in this chondrosarcoma cell line." (PMID 23825960, 2013).
colorectal carcinoma (1 paper, 2012). A malignant epithelial neoplasm that arises from the colon or rectum and invades through the muscularis mucosa into the submucosa. "DEAF1 is a predominantly nuclear protein, and changes in its subcellular location to cytoplasmic, correlate with proliferative status of cells (e.g., in colorectal carcinoma)." (PMID 22723967, 2012).
microcephaly (1 paper, 2016). A congenital or acquired developmental disorder in which the circumference of the head is smaller than normal for the person's age and sex. "One of the novel interactors predicted for IFITM3 is DEAF1, mutations in which has been linked to white matter disease, microcephaly and syndromic intellectual diability using whole exome sequencing." (PMID 29333229, 2016).
sarcopenia (1 paper, 2025). Progressive decline in muscle mass due to aging which results in decreased functional capacity of muscles. "Reducing DEAF1 expression in these contexts reversed age-related muscle weakness associated with sarcopenia." (PMID 39925192, 2025). "Elevating DEAF1 levels in muscles rescued cancer-induced defects in muscle regeneration, underscoring the critical role of the FOXOs–DEAF1–autophagy pathway in muscle health and its implications in sarcopenia and cancer cachexia." (PMID 39925192, 2025). "Interestingly, DEAF1 expression is elevated in MuSCs from aged mice and in muscles of patients with sarcopenia." (PMID 39925192, 2025).
viral infection (1 paper, 2013). "The mRNAs encoding IFNβ-dependent genes, such as IRF7, IFNα4, and IFNα6, as well as CXCL10 an established marker of viral infection, were also suppressed in DEAF1−/− MEFs." (PMID 23846693, 2013).
cancer (5 papers, 2012 to 2025). A tumor composed of atypical neoplastic, often pleomorphic cells that invade other tissues. "In humans, DEAF1 has been implicated in various neurodevelopmental disorders, autoimmune diseases and cancers." (PMID 39925192, 2025). "Deformed Epidermal Autoregulatory Factor 1 (DEAF1) is a transcription factor linked to suicide, cancer, autoimmune disorders and neural tube defects." (PMID 22442688, 2012). "Importantly, many of the MYND-containing proteins are associated with cancer and other diseases (e.g. ZMYND10, ZMYND11/BS69, ETO (eight-twenty-one)/MTG (myeloid translocation gene) family members, DEAF1, and Suppressin." (PMID 23408894, 2013). "In contrast, the expression of hnRNP, a repression target of DEAF1 that is seen at high levels in some cancers, may be free to accumulate if other DEAF1 complexes are unable to form." (PMID 22723967, 2012).
neurodevelopmental disorder (5 papers, 2021 to 2024). A behavioral and cognitive disorder with onset during the developmental period that involves impaired or aberrant development of intellectual, motor, or social functions. "This aberration contains many genes, but the most relevant is DEAF1, whose mutations are associated with neurodevelopmental disorders and the autosomal dominant Vulto–van Silfhout–de Vries syndrome." (PMID 38539661, 2024). "Also, we have identified 15 de novo variants in genes that were previously implicated in ASD or related neurodevelopmental disorders (PHF21A, WASF1, TCF20, DEAF1, MED13, CREBBP, KDM6B,SMURF1, ADNP, CACNA1G, MYT1L, KIF13B, GRIA2, CHM, and KCNK9)." (PMID 38572415, 2024). "Among them, the transcription factor Deaf1 (deformed epidermal autoregulatory factor 1) has been previously implicated in early development and innate immunity in Drosophila and in human neurodevelopmental disorders but not in muscle growth." (PMID 34780463, 2021).
infection (2 papers, 2013 to 2019). The state of being infected such as from the introduction of a foreign agent such as serum, vaccine, antigenic substance or organism. "Infection with Sendai virus also induced the association of the IFNβ promoter with DEAF1, as judged by its immunoprecipitation with anti-DEAF1 from the extracts of Sendai virus-infected wild type MEFs." (PMID 23846693, 2013). "It is interesting to note that, since increased IFNβ secretion can restrict HIV viral replication and spreading, the silencing of DEAF1 can confer a significant advantage in maintaining the potency of infection." (PMID 31178771, 2019). "The production of IFNβ mRNA and IFNβ secretion induced by infection with Sendai virus was reduced considerably in MEFs from DEAF1−/− mice compared with wild type controls." (PMID 23846693, 2013). "We showed that infection with Sendai virus enriched the association of IRF3 with IFNβ promoters in MEFs from wild type mice, which was maximal after 2 h, but this did not occur in MEFs from the DEAF1−/− mice." (PMID 23846693, 2013).
neurological disorders (1 paper, 2014). "DEAF1 is a transcriptional regulator associated with autoimmune and neurological disorders and is known to bind TTCG motifs." (PMID 25531106, 2014).
DEAF1 also shares sentences with these, for which no sentence is quoted: adenosquamous carcinoma (1 paper); mental disorder (1); Mental retardation, autosomal dominant 24 (1); Obesity (1); obsessive-compulsive disorder (1); panic disorder (1); skin melanoma (1); tumor (1).